HIF1A (hypoxia inducible factor 1 subunit alpha)
Diseases named in the same sentence as HIF1A in open-access papers (continued):
Sharing a sentence is not in itself a finding about the gene and the disease.
Hyperglycemia (continued). "Accumulation of HIF-1α protein could be detected by immunohistochemistry in retinal tissue from STZ mice after as little as 1 month of sustained hyperglycemia." (PMID 37227777, 2023). "Streptozotocin-induced hyperglycemia led to increased HIF-1α levels." (PMID 37637673, 2023). "Inhibition of SET7/9 methyltransferase activity by Set7_1a led to reduced HIF-1α methylation at the lysine 32 residue, causing increased HIF-1α level and recruitment of HIF-1α target genes that promote angiogenesis, such as VEGF, GLUT1, and EPO, in hypoxia and hyperglycemia." (PMID 35859119, 2022). "The western blot results showed that DMOG treatment could further increase the expression of HIF-1α in diabetic mice, but 2-ME inhibited the increase of HIF-1α induced by hyperglycemia." (PMID 36017378, 2022). "Therefore, it is very important to clarify the relationship between HIF-1α and poor response in patients with hyperglycemia receiving pre-operative CCRT." (PMID 36011045, 2022). "The overexpression and activity of HIF-1α may be one of the compensatory responses to hyperglycemia-related injury." (PMID 36017378, 2022). "Moreover, the mitophagy induced by hyperglycemia can be further induced by HIF-1α agonist DMOG but inhibited by HIF-1α antagonist." (PMID 36017378, 2022). "The observed down-expression of pancreatic HIF-1α gene following IPCs transplantation could be attributed to their ability in controlling hyperglycemia as reported in the present investigation, which is the leading factor of hypoxia." (PMID 36248064, 2022). "To explore the reasons for the poor response and inferior efficacy of pre-operative CCRT in rectal cancer patients with hyperglycemia, we performed HIF-1α immunohistochemical staining and scored it according to the degree of staining of patient’s tissue samples." (PMID 36011045, 2022). "The mechanism may be that hyperglycemia impairs the function of HIF-1α inhibitors and weakens the resistance of HIF-1α inhibitors to tumor chemotherapy or radiotherapy." (PMID 36011045, 2022). "However, the relationship between Parkin and HIF-1α under the hyperglycemia condition is still unclear." (PMID 36017378, 2022). "Moreover, in the 1BR.3.N WWOX KO cell line we recognized the increase of HIF1α transactivation function in hypoxia hyperglycemia condition." (PMID 35328751, 2022). "In addition, the protein levels of Hif-1α and HO-1 were dramatically decreased under hyperglycemia, whereas they were increased by Lira." (PMID 34483951, 2021). "However, the specific mechanism of HIF-1α-mediated EC protection under hyperglycemia and hypoxia is currently not fully understood." (PMID 34479471, 2021). "Indeed, the HIF-1A (also known as HIF1A) Pro582Ser polymorphism, which is resistant to inhibition by hyperglycaemia, is protective against the development of severe diabetic retinopathy." (PMID 33496820, 2021). "The recognition that NER genes including XPC, XPA, XPD, CSA, CSB, and XPG possess HREs prompted us to interrogate whether hyperglycemia-induced destabilization of HIF-1α contributed to NER attenuation." (PMID 34426491, 2021). "On the contrary, miR-126 mimic prevented the upregulation of HIF-1α expression and counteracted the increased levels of VEGF-A induced by hyperglycemia, suggesting that HIF-1α may be an indirect target of miR-126 in ARPE-19 cells." (PMID 33709000, 2021). "Interestingly, hyperglycemia has also been reported to induce HIF-1α upregulation in renal and vascular cells." (PMID 34572324, 2021). "Although the effect of hyperglycemia on HIF-1α and select NER proteins in our db/db mice mimicked that observed in cells cultured without exogenous insulin, a potential confounding effect of hyperinsulinemia on NER protein expression in this T2D model cannot be ruled out." (PMID 34426491, 2021).
Hyperglycemia (continued). "In turn, HIF-1α can be up-regulated during inflammation, while the downregulation of HIF-1α expression can effectively reduce injury caused by inflammation and oxidative stress during hyperglycemia-induced stress in ECs." (PMID 34479471, 2021). "Hypoxia causes the upregulation of HIF-1α, although HIF-1α increase may also occur as a direct consequence of hyperglycaemia independently on hypoxia." (PMID 35046830, 2021). "It has been postulated that the enhanced activity of HIF-1α may provide increased adaptability for pseudohypoxia induced by hyperglycemia." (PMID 32658866, 2020). "This led to a consensus that hyperglycemia was responsible for decreased HIF-1α protein levels." (PMID 33013447, 2020). "We measured the effect of hyperglycemia on the HIF1α/VEGF signaling pathway." (PMID 31396159, 2019). "We found that HIF‐1α was up‐regulated after 5 days of hyperglycaemia." (PMID 31094072, 2019). "Furthermore, we have provided new mechanistic insights into the regulation of HIF-1α Pro582Ser in hyperglycemia." (PMID 31214621, 2019). "Thus, inhibition of SP1/ROBO4 under hyperglycaemia or HIF‐1α/ROBO4 under hypoxia reduced cell motility." (PMID 31094072, 2019). "The relative resistance of the HIF-1A Pro582Ser polymorphism to the repressive effect of hyperglycemia is due to the transactivation activity rather than the protein stability of HIF-1α." (PMID 31214621, 2019). "Indeed, we found that salidroside treatment restored HIF-1α protein accumulation, which was suppressed by hyperglycemia; while overexpression of PHD3 cancelled this effect." (PMID 29228603, 2017). "The hyperglycemia that develops may drive HIF1α stabilization, perhaps compounding GSIS impairment further in a feedback loop." (PMID 28954230, 2017). "This study showed that anti-apoptotic chrysin may antagonize hyperglycemia-induced retinal angiogenesis and neovascularization through suppressing the up-regulation of HIF-1α, VEGF, and VEGFR2 in the retinal vasculature." (PMID 27918469, 2016). "Patients with hyperglycemia have higher serum HIF-1α levels, accordingly." (PMID 24564828, 2014). "In acute hyperglycemia-induced hemorrhagic transformation in a rat model of focal cerebral ischemia, the inhibition of HIF-1α and its downstream genes attenuated hemorrhagic transformation (extravasation of blood cellular elements), reduced cerebral infarction and ameliorated neurological deficits." (PMID 25328819, 2013). "However, these responses cause a further decline in cellular ATP level evoking a hypoxic-like response (HIF-1α activation) under hyperglycemia and normoxia." (PMID 22474421, 2012). "The authors suggested that increased levels of MGO under hyperglycemia induce HIF-1α and p300 modifications, which were sufficient to disrupt the interaction between HIF-1α/HIF-1β and HIF-1α/p300, leading to loss of HIF-1 transcriptional activity and poor response to hypoxia." (PMID 21124777, 2010). "However, chronic hyperglycemia may disrupt the normal function of HIF-1α, resulting in dysregulation of its signaling pathway." (PMID 40867634, 2025). "This may be because hyperglycemia and high fatty acid concentrations destabilize HIF-1α." (PMID 39456823, 2024). "We investigated, using an in vitro hyperglycaemia bone tissue engineering model (and a multidisciplinary bone characterisation approach), the differing effects of glucose levels, hypoxia and chemicals known to stabilise HIF-1α (CoCl2 and DMOG) on bone formation." (PMID 35977987, 2022). "It is interesting to speculate on the mechanism of hypoxia mimetic restoration of bone mineralisation in hyperglycaemia, and a possible explanation could include the reduction of ROS through HIF-1α mediated generation of ROS scavengers, and modification of glycolysis." (PMID 35977987, 2022). "Moreover, the HIF-1α inhibitor, LW6, could increase the efficacy of radiotherapy for hyperglycemia ectopic rectal cancer by inhibiting HIF-1α expression." (PMID 36011045, 2022).
Hyperglycemia (continued). "However, hyperglycemia can reduce the stability of HIF-1α, which leads to tissue fibrosis." (PMID 36250071, 2022). "Besides, down‐regulating the expression of HIF‐1α, which was dramatically increased in DM rats, could reverse hyperglycaemia damages such as vascular dysfunction and occlusion." (PMID 34114347, 2021). "However, the underlying mechanisms facilitating PHD- and VHL-mediated HIF-1α degradation during hyperglycaemia are still not fully understood." (PMID 33496820, 2021). "In conclusion, this study identifies HIF-1α and related cellular energetic changes (i.e., Warburg effect) as early and essential components of a metabolic and chemical process that mediates the injurious effect of hyperglycemia, leading to cell activation and inflammation." (PMID 34572324, 2021). "Moreover, hyperglycemia destabilizes HIF-1α, which is the regulatory subunit of HIF-1." (PMID 34883634, 2021). "However, direct targeting of HIF-1α or PHD2 in diabetic animal models cannot provide further comprehension of their role in the instigation of the initial cellular biochemical abnormalities induced by hyperglycemia, which is the aim of this study." (PMID 34572324, 2021). "Therefore, the accumulation of HIF-1α caused by hyperglycemia substantially aggravates BBB damage in diabetic stroke, and therapeutic treatments targeting HIF-1α may provide new treatment options for preventing hemorrhagic transformation in these patients." (PMID 34966392, 2021). "Therefore, this study focuses on whether the HIF-1α/MIF/AMPK signaling pathway is a key point in mediating the protective effect of SPostC in hyperglycemia." (PMID 33692685, 2020). "Despite the preserved sensitivity to the destabilizing effect of hyperglycemia, the transactivation activity of HIF-1α Pro582Ser is increased even in high glucose concentration, which might explain the protective effect of the HIF-1A Pro582Ser polymorphism for the risk for severe NPDR/PDR." (PMID 31214621, 2019). "Moreover, the relative resistance of the HIF-1A Pro582Ser polymorphism to the repressive effect of hyperglycemia is due to the transactivation activity rather than the protein stability of HIF-1α." (PMID 31214621, 2019). "Although cancer cells need more glucose than normal cells to maintain energy demand, chronic hyperglycemia induces metabolic alteration that may dysregulate signaling pathways, including the O-GlcNAcylation and HIF1A (Hypoxia-inducible factor 1-alpha) pathways." (PMID 30217067, 2018). "Hyperglycemia might promote HIF-1α protein synthesis and a hypoxic microenvironment." (PMID 30455857, 2018). "Therefore, it might very well be that in T2DM patients, chronic hyperglycemia and oxidative stress contributes to the HIF-1α- regulated metabolic change in peripheral blood cells." (PMID 25956355, 2015). "Moreover, superoxide induced by hyperglycemia may destabilize HIF-1α and reduce the activation of SDF-1α, VEGF and CXCR4 in response to hypoxia." (PMID 26305217, 2015). "Studies suggest that hyperglycaemia leads to impaired HIF‐1 signalling pathways, weakening HIF‐1α mediated responses to hypoxia and resulting in the downregulation of its downstream target genes, ultimately leading to non‐healing diabetic foot ulcers." (PMID 40758539, 2025). "Moreover, hyperglycemia could impede the expression of HIF‐1α, an anti‐inflammatory hypoxia‐inducible factor‐1α, thereby disrupting the NLRP3/IL‐1β signaling pathway and influencing T lymphocyte differentiation, thereby compromising the body's anti‐inflammatory response against Aspergillus." (PMID 40860300, 2025). "Hyperglycemia promotes SARS-CoV-2 infection and monocyte activation via an HIF-1α-dependent mechanism on glycolysis, resulting in mitochondrial ROS and HIF-1α stabilization." (PMID 41488672, 2025). "What’s more, hyperglycemia also induces methylglyoxal (MGO) accumulation, which induces the degradation of HIF-1α and decreases the transcriptional activity of HIF-1." (PMID 37251664, 2023).
Hyperglycemia (continued). "Here, we not only confirmed that patients with clinical hyperglycemia have a poor CCRT prognosis, but also confirmed that the expression level of HIF-1α in rectal cancer is higher than other euglycemic rectal cancer patients." (PMID 36011045, 2022). "In hypoxia and hyperglycemia, SET7/9 plays an important role in controlling HIF-1α methylation and regulating the transcription of HIF-1α target genes, which are responsible for angiogenesis and wound healing." (PMID 35859119, 2022). "This was further confirmed by similar results that were observed when HIF-1 activity was maintained during hyperglycemia in hypoxia by genetic approaches, that is silencing VHL that mediates HIF-1α degradation or overexpressing HIF-1α." (PMID 35164902, 2022). "Hyperglycemia-induced methylglyoxal modifies p300 and disrupts the binding of p300 to HIF-1α, thereby leading to the destabilization of HIF-1α and the downregulation of HIF-1α-related responses under hypoxic conditions." (PMID 35684364, 2022). "Notably, hyperglycemia was able to decrease HIF-1α stabilization even in the presence of the PHD inhibitor EDHB in both hypoxia and normoxia, suggesting that mechanisms other than proline hydroxylation may be involved in the regulation of HIF-1α protein turnover in diabetes." (PMID 35859119, 2022). "Both hyperglycemia and AGEs/ALEs promote the protein accumulation of HIF-α proteins—mainly HIF-1α—and HIF activity in glomerular mesangial and renal tubular epithelial cells in in vitro and in vivo models of DKD." (PMID 36358555, 2022). "In summary, hyperglycemia increases TGF-β and HIF1α expression, which in turn elevates rates of glycolysis and lactic acid production with the consequently increased collagen synthesis, acidification, expansion, and lower degradation of ECM." (PMID 35563220, 2022). "Hyperglycemia upregulates TGF-β and hypoxia-inducible factor 1 subunit alpha (HIF1α) expression by increasing the glycolytic rate and inhibiting pyruvate dehydrogenase complex (PDH), promotes the production of lactic acid." (PMID 35563220, 2022). "It is well known that transcription of VEGF-A is regulated by hypoxia-inducible factor 1-alpha (HIF-1α), a transcription factor that is the master regulator of cellular response to hypoxia and hyperglycemia." (PMID 33709000, 2021). "This was confirmed in an in vivo model of GDM showing that hypoxia inducible factor-1α (HIF-1α) and VEGF levels were significantly higher in placentae in the presence of hyperglycaemia." (PMID 34149611, 2021). "Hyperglycaemia results in the upregulation of TGF-beta and hypoxia-inducible factor 1 subunit alpha (HIF1α) expression." (PMID 34360717, 2021). "Hyperglycemia affects HIF-1α stability and activation and consequently it suppresses HIF-1α target genes like VEGF." (PMID 32244718, 2020). "In addition, hyperglycemia may impair the stabilization and transactivation of HIF-1α." (PMID 32658866, 2020). "Subsequently, we showed that hyperglycemia suppressed macrophage activation via the downregulation of the GLUT1 receptor, which is a transcriptional target of HIF-1α." (PMID 31546645, 2019). "Previous studies reported that hyperglycemia, even in hypoxic conditions, negatively affects the stability and activation of HIF-1α and inhibits the expression of target genes of HIF-1α, which are critical to wound healing." (PMID 30791543, 2019). "Knockdown of HIF‐1α significantly inhibited SP1 and ROBO4, whereas SP1 down‐regulation abolished ROBO4 expression in RPE cells under hyperglycaemia/hypoxia." (PMID 31094072, 2019). "For example, inhibition of HIF-1α and VEGF reduced HT in the ischemic brain which was induced by acute hyperglycemia and inhibition of HIF-1α-VEGF signaling reduced BBB damage in rat neonatal stroke model." (PMID 30233326, 2018).
Hyperglycemia (continued). "Besides, hyperglycaemia appeared to down-regulated HIF-1α mRNA expression in ischaemic myocardium, and inhibited the defective response of HIF-1α to ischaemia, explaining a positive association between hyperglycaemia at the time of the event and subsequent mortality from myocardial infarction." (PMID 28595632, 2017). "For example, HIF-1α up-regulates VEGF and leads to BBB disruption, while suppression of HIF-1α and VEGF reduces acute hyperglycemia-induced HT in the ischemic brain." (PMID 28855859, 2017). "In the present study, we have shown that hyperglycemia promotes the degradation of HIPK2 in parte through ubiquitin ligase Siah2 downstream of a protein cascade including PP2A and HIF-1α, as summarized in the scheme." (PMID 27901482, 2017). "In this study, we found that hyperglycemia induces PHD3 protein accumulation in skeletal muscle cells, which in turn decreases HIF-1α protein accumulation, and subsequently impairs the paracrine functions of skeletal muscle cells." (PMID 29228603, 2017). "Hyperglycemia had previously been proved to impair hypoxia-induced stabilization of HIF-1α protein without known mechanisms." (PMID 37470788, 2024). "Because hyperglycemia can result in GSK3β activation, these studies suggested that CHIP and FBW7 may cooperate to mediate the degradation of HIF-1α in hypoxia." (PMID 37470788, 2024). "The lack of this SNP among T2DM patients makes HIF-1α unstable and degraded faster by the effects of hyperglycemia and hyperlipidemia." (PMID 35969320, 2022). "However, there are studies showing that hyperglycemia in diabetic patients impair the HIF pathway, differing with studies which show an increased expression of HIF1-α under hyperglycemia." (PMID 34225729, 2021). "However, PHD inhibition or VHL inactivation can largely rescue HIF-1α stability, indicating an important role for PHD and VHL in mediating the degradation of HIF-1α during hyperglycaemia." (PMID 33496820, 2021). "The cardioprotective of SPostC could be restored by upregulating the protein expression of HIF-1α and MIF under hyperglycemia." (PMID 33692685, 2020). "Additionally, HIF‐1α, SP1 and ROBO4 co‐expressed in the diabetic retina and in RPE cells under hyperglycaemia." (PMID 31094072, 2019). "Furthermore, CGRP suppressed the increased HIF-1α/VEGF-A expression and the phosphorylation of ERK1/2 in hyperglycemia." (PMID 31487015, 2019). "The canonical oxygen-dependent regulation of HIF-1α is dependent on the hydroxylation of at least two critical prolines (Pro402/Pro564) that makes it accessible to VHL-dependent degradation, which is central for the effect of hyperglycemia on HIF." (PMID 31214621, 2019). "In order to address this issue, we first studied the response under hyperglycemia of the HIF-1α-HRE pathway in HK-2 immortalized PTC cells in which the canonical oxygen-, iron-PHD-pVHL-ubiquitin-dependent proteasome pathway of HIF-1α degradation had been inhibited at different levels." (PMID 31676796, 2019). "Thus, HIF‐1α, SP1 and ROBO4 had important regulatory roles in RPE cells under hyperglycaemia or hypoxia." (PMID 31094072, 2019). "Additionally, HIF‐1α, SP1 and ROBO4 levels were elevated concomitantly in vivo in a model of DR and in vitro in RPE cells cultured under hyperglycaemia or hypoxia." (PMID 31094072, 2019). "Inhibition at different levels of the canonical pathway of HIF-1α degradation did not activate the HIF-1/HRE response under hyperglycemia, except when proteasome was inhibited." (PMID 31676796, 2019). "WB revealed a significant increase in HIF-1α protein at 1 h of CoCl2 under euglycemia-CoCl2 (3.4-fold, p < 0.01) but no significant increase under hyperglycemia-CoCl2." (PMID 29351188, 2018). "Apart from this, chronic hyperglycemia stimulates synthesis and secretion of vascular endothelial growth factor (VEGF), which was transcriptional regulated by hypoxia-inducible factor-1α (HIF-1α), is the major growth factor mediating retinal vascular leakage and neovascularization." (PMID 27649243, 2016).